MYC (MYC proto-oncogene, bHLH transcription factor)
Diseases named in the same sentence as MYC in open-access papers (continued):
Sharing a sentence is not in itself a finding about the gene and the disease.
lung adenocarcinoma (continued). "In addition, obviously higher expression of oncogenes c-MYC, WNT1, WNT2, and NOTCH1 was detected in side population (SP) cells than in non-side population (NSP) cells of human lung adenocarcinoma cell line-A549, revealing a possible mechanism for the tenacious tumorigenic potential of CSCs." (PMID 22615765, 2012).
cervical carcinoma (163 papers, 2008 to 2026). A carcinoma arising from either the exocervical squamous epithelium or the endocervical glandular epithelium. "Although upregulation of MYC is prevalent in HPV‐associated cervical cancer, MYC‐targeted therapy remains a challenge for a couple of reasons." (PMID 36691316, 2023). "The more common rs6983267(G) polymorphism variant of the CCAT2 gene has been shown to be associated with increased MYC gene expression levels and accelerated cervical cancer progression." (PMID 34440124, 2021). "Recently, it has been reported that the integrated HPV fragment creates long-distance interactions with MYC gene and 8q24.22 region, therefore, increasing the allele-specific MYC expression in cervical cancer HeLa cells." (PMID 29525942, 2018). "Amplification, rearrangement or hypomethylation of the MYC oncogene are genetic alterations frequently occurring in many cancers, as carcinoma of the cervix, colon, breast, lung and stomach, and causing MYC to be activated and over-expressed." (PMID 26453442, 2015). "However, HPV E6 and E7 knockdown causes a drastic decrease in MYC expression, potentially leading to reduced viability of cervical cancer cells." (PMID 40299341, 2025). "We show that human papillomavirus (HPV) integrations in cervical cancers alter host 3D chromatin contacts and cause over‐expression of genes (including MYC, TP63 and ERBB2), which are mostly confined within the topologically associating domains with integration." (PMID 38013620, 2024). "Interestingly, we first found that USP45 was highly expressed in cervical cancer tissues and associated with MYC signaling pathways." (PMID 36765885, 2023). "The MYC gene family and its products promote cervical cancer cell proliferation, immortalization, dedifferentiation, and transformation; furthermore, they can be used as a potential diagnostic indicator for cervical cancer." (PMID 31516392, 2019). "Beyond these genes, miRNAs also play a crucial role in regulating transcription factors such as SP1 and MYC, which are pivotal drivers of cervical cancer progression." (PMID 40817807, 2025). "Specifically, METTL3-catalyzed m6A methylation enhances MYC mRNA translational efficiency, thereby driving cervical carcinoma tumorigenesis through MYC-dependent cell cycle dysregulation." (PMID 40986143, 2025). "Prior studies in gastric, lung, and cervical cancers have suggested that ASF1B modulates cell cycle regulators such as Cyclin E1, CDK2, and MYC, consistent with our enrichment results showing associations with DNA replication and mitotic pathways." (PMID 40944429, 2025). "The current investigation elucidated that CEBPD serves as an upstream regulatory factor for key genes, including MYC, IL6, JUN, RRM2, and VEGFA, all of which have been linked to an unfavorable prognosis in cervical cancer patients." (PMID 38926832, 2024). "Recently, it was reported that HR-HPV 16/18 infection in cervical cancer stabilized m6A-methylated MYC expression by regulating IGF2BP2, an m6A reader, further promoting aerobic glycolysis." (PMID 38784389, 2024). "This study suggested that miR-145 influences aerobic glycolysis through its interaction with MYC, presenting it as a potential therapeutic target for the management of cervical cancer." (PMID 38926832, 2024). "Hi‐C and 4C‐seq analyses in cervical cancer cell line (HeLa) demonstrated chromatin looping interactions between integrated HPV and MYC/PVT1 regions (~ 500 kb apart), leading to allele‐specific overexpression." (PMID 38013620, 2024). "In cervical cancer, the MYC protein was recently identified as a direct substrate of the m6A demethylase FTO and FTO-mediated demethylation boosts the translational efficiency of MYC mRNA." (PMID 38273337, 2024).
cervical carcinoma (continued). "IGF2BP2 can recognize m6A modification sites in MYC mRNA in cervical cancer cell lines to promote MYC expression, thereby enhancing cancer cell proliferation, migration, invasion, and aerobic glycolysis." (PMID 38343637, 2024). "Their findings revealed significantly elevated c-MYC expression in cervical cancer tissues compared to normal cervical and cervical intraepithelial neoplasia (CIN)." (PMID 38926832, 2024). "Extending the earlier work on organoid culture establishment, recent efforts used whole-exome sequencing and transcriptome analyses to identify upregulated MYC expression and activating KRAS mutations in patient-derived cervical cancer organoids." (PMID 37173984, 2023). "Deregulated expression or function of MYC is one of the most common abnormalities in human malignancy including cervical cancer." (PMID 36763589, 2023). "On the basis of our investigations, we have discovered that USP45 as a new deubiquitinase of MYC significantly promoted cervical cancer development, stemness and drug resistance." (PMID 36765885, 2023). "Further, we have discovered that USP45 was a novel deubiquitinating enzyme of MYC, and its overexpressing enhanced cervical cancer stemness and drug resistance." (PMID 36765885, 2023). "Subsequently, to assess the association between MYC expression levels and cell sensitivity to the MYC inhibitor, the cell sensitivity of SCCC organoids was compared to other cervical cancer cell lines, HeLa, CaSki, SiHa, and C33a." (PMID 36691316, 2023). "We demonstrated that USP45 inhibition via destabilizing MYC suppressed the stemness and drug resistance of cervical cancer cells." (PMID 36765885, 2023). "SALL4 activates MYC and Cyclin D1 by upregulating the Wnt/β-catenin pathway in cervical cancer cells." (PMID 33947962, 2021). "To determine the function of these genes in human cervical cancer, we examined the expression of DEC1, DEC2, SOX2 and c-MYC in human cervical cancer tissues." (PMID 33089188, 2020). "We showed that the strong ratio of SOX2 expression in cervical cancer cells was 80%, but the ratio of c-MYC was 35%." (PMID 33089188, 2020). "This haplotype information importantly allowed the authors to conclude that MYC was cis-activated by the inserted HPV18 (human papilloma virus) DNA in this cervical cancer cell line." (PMID 33317567, 2020). "c-MYC is often upregulated leading to increased expression of several genes involved in cell proliferation and cancer development such as carcinoma of the cervix, colon, breast, lung, and stomach." (PMID 33575208, 2020). "The abundancy of c-MYC protein in expanded MSC from bone marrow reached higher levels than in the cervical cancer cell line HeLa that is known to induce tumors in a mouse xenograft model." (PMID 30836996, 2019). "Another study indicated that MYC (8q24) played a vital part in the progression of CIN to cervical cancer." (PMID 31255182, 2019). "Of note, because PVT1 and MYC are frequently co-amplified in cancer, we additionally examined expression of MYC in cervical cancer and adjacent normal tissues." (PMID 27232880, 2016). "Since it is well documented that MYC promotes cell proliferation in cervical cancer and in squamous intraepithelial lesions of the uterine cervix, it is possible that miR-210 is involved in cervical carcinogenesis through the promotion of MYC overexpression." (PMID 24490161, 2013). "c-MYC has been confirmed to be involved in the regulation of aerobic glycolysis in cervical cancer." (PMID 40379626, 2025). "Leveraging miRNAs to concurrently target transcription factors such as SP1 and MYC may provide synergistic therapeutic benefits, paving the way for innovative combination strategies that exploit the vulnerabilities of cervical cancer." (PMID 40817807, 2025).
cervical carcinoma (continued). "The USP25/KIFC1/MYCBP signal axis detected by RT-PCR did not change the expression level of c-MYC mRNA, but affected the expression levels of c-MYC transcription targets CDK4, CDK2, cyclin D1 and cyclin E which these have been reported to be regulated by c-MYC transcription in cervical cancer." (PMID 40379626, 2025). "MYC’s involvement in cervical cancer has been the subject of inquiry across multiple studies." (PMID 38926832, 2024). "Overexpression of MYC is frequently found in HPV‐infected cervical cancer." (PMID 36691316, 2023). "Furthermore, MYC expression was compared between the original SCCC tissue and 13 HPV‐associated cervical cancers; their HPV integration sites were analyzed by RNA‐seq." (PMID 36691316, 2023). "Furthermore, we have found that USP45 inhibition with a natural small molecule promoted MYC degradation and, in turn, reduced MYC-mediated stemness and drug resistance in cervical cancer." (PMID 36765885, 2023). "These bioinformatics analysis data revealed that USP45 might play a critical role in cervical cancer and activate MYC target signaling pathways." (PMID 36765885, 2023). "Thus, mutation or alteration in the expression of MYC and PIK3CA is frequently associated with development of cervical cancer." (PMID 36763589, 2023). "Research showed that root extract of P. vulgaris inhibited 12 signaling pathways in a cervical cancer cell line and the most potent activation inhibition was observed for MYC, Notch, Wnt, E2F, Ets, Stat3, Smad, Hdghog, AP-1, and NF-κB, at a concentration of 40 μg/mL." (PMID 36674653, 2023). "Furthermore, FTO and MYC have also been found to cooperate to drive cell proliferation in both pancreatic and cervical cancer." (PMID 35350378, 2022). "These genes along with MYC are already described as HPV integration hotspot in cervical cancer." (PMID 35398964, 2022). "The root extract of P. patens exhibited strong inhibition of several signaling pathways in HeLa cells, a cervical cancer cell line, and was found to be the most potent in inhibiting the activation of Stat3, Smad, AP-1, NF-κB, MYC, Ets, Wnt and Hdghog, at a concentration of 40 μg/mL." (PMID 34017038, 2021). "Collectively, DEC1, DEC2, SOX2 and c-MYC play important roles of cervical cancer progression." (PMID 33089188, 2020). "Similarly, HPV18 has been found to be integrated downstream, upstream (at POU5F1B and OCT4) or within MYC, resulting in its amplification (20 fold) and over-expression (4.3-fold induced) in cervical cancers." (PMID 27784002, 2017). "Thus, Hy has a significant inhibitory effect on the MYC gene in cervical cancer C-33A cells." (PMID 31516392, 2019). "Here we show that in HPV-transformed cervical cancer cells, MYPOP induces alterations in cell morphology, silences viral and cellular oncogenes including E6 and MYC, and stimulates the release of the cancer-killing cytokine interleukin-24." (PMID 42156885, 2026). "This binding at the m6A methylation modification site in MYC mRNA enhances both the stability and translation efficiency of MYC mRNA in HCC and cervical cancer." (PMID 39456902, 2024). "Recurrent HPV integrations near cancer‐related genes (such as MYC and TP63) have been previously reported in cervical cancers." (PMID 38013620, 2024). "Further, we have discovered that increased USP45 expression significantly promoted cervical cancer cell proliferation, stemness and drug resistance, while USP45-enhanced MYC stability facilitated only stemness and drug resistance." (PMID 36765885, 2023). "Mutations or alterations in the expression of human oncogenes, including MYC, PIK3CA and RAS, have been reported in cervical cancer." (PMID 36763589, 2023). "By binding to a locus of the MYC gene, IGF2BP2 enhances the proliferation, metastasis, and aerobic glycolysis of cervical cancer cells." (PMID 36894952, 2023).
cervical carcinoma (continued). "A study in cervical cancer suggested that FTO regulates migration by promoting the protein translation of E2F1 and MYC, two regulators of cell cycle and migration, in an m6A-dependent manner." (PMID 35350378, 2022). "In cervical cancer, FTO interacts with E2F1 and MYC to increase its translation efficiency and promote cervical cancer cell migration and proliferation." (PMID 36360287, 2022). "Quercetin exerted a synergistic effect on cisplatin-treated cervical cancer cells primarily through downregulating the protein levels of EGFR, MYC, CCND1, and ERBB2 and upregulating CASP8." (PMID 35070983, 2021). "Here, KEGG analysis revealed that MYC target and mTORC1 signaling pathways were potentially suppressed by PAMR1 in cervical cancer." (PMID 34671559, 2021). "Our results demonstrated that quercetin combined with cisplatin has a synergistic effect on cervical cancer, leading to decreased protein expression of EGFR, MYC, CCND1, and ERBB2." (PMID 35070983, 2021). "We also found that KD of WAPL in human cervical cancer cells reduced estrogen sensitivity and expression of ESR1 downstream genes, MYC and Cyclin D1." (PMID 33947962, 2021). "FTO contributes to the proliferation and migration of cervical cancer cells by directly interacting with E2F1 and MYC transcripts and impairing their translation efficiency in a demethylase‐dependent manner." (PMID 33029866, 2020). "In HPV-positive cervical cancer, viral genome integrations occur on all chromosomes, with no detectable hot spots, except for the KLF5/KLF12 gene and adjacent to the MYC gene locus." (PMID 31766658, 2019). "In cervical cancer, CIP2A functioned as an oncogene to regulate c-MYC degradation through inhibiting PP2A." (PMID 23342256, 2012). "The “GSE63514” dataset showed that USP45 expression in the cancer tissues was elevated, but MYC was not significantly changed in cervical cancer tissues, compared with the normal tissues or stage CIN I-III." (PMID 36765885, 2023). "Our results show that a few alterations of host oncogenes, such as MYC, PIK3CA, MEK1 and KRAS, in conjunction with the episomal form of HPV16, might be sufficient to drive development of cervical cancer." (PMID 36763589, 2023). "As expected, we observed its strong anticancer effect on cervical cancer cells and its downregulation affecting the MYC protein levels without interfering with the mRNA levels." (PMID 36765885, 2023). "In cervical cancer, FTO was found to promote MYC translation; however, whether this mechanism was m6A-dependent was not established." (PMID 35350378, 2022). "Interestingly, consistent with LGR6, TCF7L2, CTNNB1, MYC, and POU5F1 were all related to the poor prognosis of cervical cancer." (PMID 34489551, 2021). "Furthermore, the upregulation of CTNNB1, MYC, SOX2, and OCT4 in LGR6high cervical cancer cells was further validated by the RT-PCR assay in vitro." (PMID 34489551, 2021). "Although 8q24.21 contains the MYC oncogene, a causative role for HPV integration at this site in the pathogenesis of cervix cancer has not been established." (PMID 32544169, 2020). "This indicates that, unlike c-MYC in the 8q24 location, there was no obvious chromosomal rearrangement in the 12q13-15 region during cervical cancer tumorigenesis." (PMID 29487700, 2018). "c-MYC is one of the most important oncogenes of cervical cancer; therefore, we propose that CCAT-1 might be involved in the progression of cervical cancer as well." (PMID 28978096, 2017). "Given that MYC is a downstream target of IGF2BP2 and a crucial regulator of glycolysis, further investigations revealed that E6/E7 can modulate aerobic glycolysis in cervical cancer cells through the m6A‐MYC pathway mediated by IGF2BP2 both in vitro and in vivo." (PMID 39660878, 2024). "Likewise, MYC is a noteworthy target, particularly in HPV‐related cervical cancers." (PMID 36691316, 2023).
cervical carcinoma (continued). "Therefore, we evaluated the role of rs6983267 SNP in MYC expression in cervical cancers and non-cancerous cervical tissues." (PMID 29525942, 2018). "Collectively, these data suggest that co-regulation of PVT1 and MYC expression may not be as common in cervical cancer as it is in other cancer types and that the result of their interaction is unlike that described previously." (PMID 27232880, 2016). "Indeed, we found that significant co-occurrence of MYC amplification and PIK3CA alteration in TCGA of cervical cancer though the status of HPV genomes is not known." (PMID 36763589, 2023).